MARK4 (microtubule affinity regulating kinase 4)
Diseases named in the same sentence as MARK4 in open-access papers (continued):
Sharing a sentence is not in itself a finding about the gene and the disease.
myocardial infarction (6 papers, 2022 to 2025). Gross necrosis of the myocardium, as a result of interruption of the blood supply to the area, as in coronary thrombosis. "Recently, Mark4 was reported to regulate cardiomyocyte contractility by promoting the phosphorylation of microtubule-associated protein 4 and acted as a promising therapeutic target for improving cardiac function after myocardial infarction." (PMID 38301049, 2024). "Importantly, MARK4 deficiency significantly reduces the loss of ejection fraction following acute myocardial infarction in mouse models." (PMID 35493101, 2022). "Specifically, miR-199a-5p targets AGTR1, diminishing early oxidative damage post-myocardial infarction, and MARK4, which influences long-term myocardial contractility and enhances cardiac function." (PMID 38956062, 2024). "Notably, microtubule-affinity regulating kinase 4 (MARK4)-dependent modulation was recently discovered to be a mechanism for microtubule detyrosination during myocardial infarction." (PMID 35493101, 2022). "During this process, the phosphorylation of microtubule-associated protein 4 by microtubule-affinity-regulating kinase 4 (MARK4) gives VASHs more access to detyrosinating α-tubulin, and the loss of ejection fraction is markedly reduced in the absence of MARK4 in an acute myocardial infarction model." (PMID 40497943, 2025). "The mechanistic studies confirmed that miR199a-5p could protect the heart from myocardial infarction injury by controlling the AGTR1/NOX4 and MARK4/VASH2/dTyr-tub pathways." (PMID 38956062, 2024).
hepatocellular carcinoma (5 papers, 2016 to 2022). A malignant tumor that arises from hepatocytes. "Initially termed MARKL1 (microtubule affinity‐regulating kinase‐like 1), MARK4 was identified by a cDNA microarray approach to be down‐regulated following a decrease in TCF/LEF1 (transcription complex, T‐cell factor/lymphoid enhancer‐binding factor) activity in hepatocellular carcinoma cell lines." (PMID 26882547, 2016).
prostate carcinoma (4 papers, 2017 to 2022). A carcinoma that arises from epithelial cells of the prostate gland. "MARK4 is a key component of the Wnt signaling system that has been connected to prostate cancer caused by Wnt." (PMID 35936719, 2022). "MARK4 is an important component of the Wnt signaling system, and linked to Wnt-induced prostate cancer." (PMID 35936719, 2022).
tauopathy (4 papers, 2016 to 2025). Neurodegenerative disorders involving deposition of abnormal tau protein isoforms (tau proteins) in neurons and glial cells in the brain. "The interaction between subcortical axonal ischemia and the up-regulation of a gene (Mark4) implicated in AD suggests a potential two-hit hypothesis for tauopathy related to dementia." (PMID 31429800, 2019). "Our results demonstrate that lowering MARK4 levels is sufficient to ameliorate the tauopathy phenotype in a mouse model, suggesting its critical involvement in neurodegenerative pathology." (PMID 38712317, 2024). "Here, we demonstrated that Mark4 deletion ameliorated the tau pathology in a mouse model of tauopathy." (PMID 38712317, 2024). "Our results suggest that MARK4 is a reasonable target for the identification of novel tauopathy treatments." (PMID 38712317, 2024). "This study shows that lowering MARK4 levels reduces pathological tau aggregates and astrogliosis and ameliorates neurodegeneration and behavioural deficits in a mouse model of tauopathy, suggesting MARK4's critical role in disease pathogenesis." (PMID 38712317, 2024). "This study highlights the importance of MARK4 as a viable target for Tauopathy and provides fresh insight into the complex mechanism used by MB to treat AD." (PMID 27708431, 2016). "Our data indicate that MARK4 critically contributes to tau-mediated neuropathology, suggesting that MARK4 inhibition may serve as a therapeutic avenue for tauopathies." (PMID 38712317, 2024). "Here, we examined MARK4 involvement in the disease pathogenesis of a tauopathy mouse model (PS19)." (PMID 38712317, 2024). "Knockdown of MARK4 and administration of DEPTAC to dephosphorylate tau offer promising approaches to slowing the progression of AD and related tauopathies." (PMID 40038800, 2025). "To investigate the role of MARK4 in tau-mediated neuropathology, we crossed P301S tauopathy model (PS19) and Mark4 knockout mice." (PMID 38712317, 2024).
heart failure (3 papers, 2021 to 2025). Inability of the heart to pump blood at an adequate rate to meet tissue metabolic requirements. "Recently, MARK4 has also been implicated in heart failure in mice." (PMID 40332117, 2025). "Animal models of heart failure revealed elevated MARK4 levels, which correlated with impaired cardiac contractility." (PMID 40332117, 2025). "In the late stages, when cardiac contractile function was weakened, miR199a-5p enhanced myocardial contractility to mitigate post-infarction heart failure via targeting MARK4." (PMID 38956062, 2024). "We demonstrated that impaired cardiac contractility (decreased LVEF) as well as nocturnal hypoxia (decreased mean SpO2) are independently associated with an increased myocardial MARK4 expression, thereby suggesting MARK4 as a potential molecular target for heart failure therapy." (PMID 40332117, 2025). "Furthermore, the inverse relationship between MARK4 expression and LVEF, alongside its induction under hypoxic conditions, suggests an important role in heart failure pathophysiology." (PMID 40332117, 2025). "The development of MARK4 inhibitors is the subject of current research but primarily in the context of neurodegenerative diseases and cancer rather than heart failure." (PMID 40332117, 2025).
hyperglycaemia (3 papers, 2020 to 2024). "In conclusion, ELF3 interacted with SET8 to modulate MARK4 expression, which participated in hyperglycaemia-mediated endothelial NLRP3 inflammasome activation." (PMID 32439949, 2020). "In this case, we still observed that the MARK4 intervention regulated myocardial lipid oxidation metabolism, but whether this regulatory effect is jointly affected by MARK4 and hyperglycaemia itself is unknown." (PMID 38839927, 2024). "In the present study, we hypothesized that ELF3 may increase MARK4 expression, thus playing a crucial role in hyperglycaemia-induced NLRP3 inflammasome activation in vascular endothelial cells." (PMID 32439949, 2020). "Microtubule affinity regulating kinase 4 (MARK4) has been reported to play a crucial role in the regulation of NLRP3 inflammasome activation and may be a potential target for hyperglycaemia-mediated NLRP3 inflammasome activation and endothelial inflammation." (PMID 32439949, 2020).
Ataxia (2 papers, 2015 to 2024). Ataxia refers to impaired coordination of voluntary muscle movement. "She revealed that MARK4 acts in concert with another kinase, TTBK2, which was shown to play similar functions to MARK4 in ciliogenesis and is implicated in spinocerebellar ataxia." (PMID 25974046, 2015). "PS19:Mark4+/− and PS19:Mark4−/− obtained by crossing PS19:Mark4+/− and Mark4+/− (F2) showed less number of mice developing ataxia compared with PS19 by 9 months old." (PMID 38712317, 2024).
diabetic cardiomyopathy (2 papers, 2024 to 2025). Diabetic cardiomyopathy is a disorder of the heart muscle in people with diabetes. "In this study, after successful establishment of a diabetic cardiomyopathy model induced by streptozotocin and a high-fat diet, MARK4 expression was found to be significantly increased in STZ-induced DCM mice." (PMID 38839927, 2024).
glioblastoma (2 papers, 2013 to 2022). The most malignant astrocytic tumor (WHO grade IV). "Interestingly, MARK4 appears to undergo gene amplification in glioblastoma cell lines, resulting in overexpression the MARK4L isoform and increased proliferate capacity." (PMID 24144331, 2013).
ischemia (2 papers, 2019 to 2025). A hypoperfusion of the BLOOD through an organ or tissue caused by a PATHOLOGIC CONSTRICTION or obstruction of its BLOOD VESSELS, or an absence of BLOOD CIRCULATION. "Recently, we demonstrated an increase in the amount of both MAP4 and phosphorylated MAP4 by microtubule affinity-regulated kinase 4 (MARK4) in mouse cardiomyocytes after ischemia." (PMID 40678799, 2025). "Despite these challenges, we show definitive evidence that up-regulation of Mark4 is a consistent response of cortical neurons to subcortical axonal ischemia." (PMID 31429800, 2019). "To confirm Mark4 up-regulation in cortical neurons after axonal ischemia, we performed laser capture microdissection of ipsilateral retrograde-labeled Layer 5 neurons 7d after stroke (453.5 ± 41.3 cells/animal, n = 8) compared to non-stroke injured Layer 5 neurons (455.8 ± 28.2 cells/animal, n = 4)." (PMID 31429800, 2019). "This cytoskeletal reorganization after subcortical axonal ischemia is consistent with the effects of Mark4 overexpression on dendritic complexity in cultured hippocampal neurons indicating that this reorganization is at least partially dependent on the regulation of tau." (PMID 31429800, 2019).
liver cancer (2 papers, 2022 to 2023). An epithelial or non-epithelial malignant neoplasm that arises from the liver. "researched that coumarin derivatives, as an inhibitor of microtubule affinity-regulating kinase 4 (MARK4), induce apoptosis of liver cancer cell by increasing microtubule dynamics and the sensitivity of paclitaxel." (PMID 36865794, 2023).
lung carcinoma (2 papers, 2016 to 2022). "In agreement with this, MARK4 protein was detectable in 37% of lung cancer samples, while it remained undetected in normal lung tissue." (PMID 26882547, 2016). "Quantitative PCR analysis of a lung cancer cDNA array revealed that MARK4 mRNA levels are increased in > 50% of tumours as compared to normal lung tissues." (PMID 26882547, 2016). "In contrast to MARK4, miR‐515‐5p expression was positively correlated with overall survival in patients with metastatic breast or lung cancer." (PMID 26882547, 2016). "In summary, we demonstrate here that miR‐515‐5p overexpression inhibits cell migration by down‐regulating MARK4 mRNA levels in both breast and lung cancer, suggesting the importance of miR‐515‐5p/MARK4 mechanism across different cancer types." (PMID 26882547, 2016). "High levels of MARK4 mRNA correlated with a lower overall survival in ER‐negative metastatic breast and lung cancer patients, although this only reached statistical significance in the latter." (PMID 26882547, 2016). "In agreement with metastasis being a poorer prognosis factor for cancer patients, decreased miR‐515‐5p or increased MARK4 expression was indicative of poorer survival in both metastatic breast and lung cancer." (PMID 26882547, 2016). "When subtypes of lung cancer were separated, MARK4 expression was especially prevalent in adenocarcinoma samples with 53% of cases for this tumour type showing positive MARK4 staining." (PMID 26882547, 2016). "To assess the clinical relevance of our findings, we first evaluated the potential of MARK4 as prognostic biomarkers in metastatic breast and lung cancer patients." (PMID 26882547, 2016). "Finally, the correlation between miR‐515‐5p/MARK4 expression and the outcome of metastatic breast and lung cancer suggests the use of miR‐515‐5p and MARK4 as prognostic molecular biomarkers for metastatic cancer patients." (PMID 26882547, 2016). "Taken together, MARK4 and/or miR‐515‐5p expression levels may be relevant prognosis markers in both breast and lung cancer." (PMID 26882547, 2016). "Moreover, high miR‐515‐5p and low MARK4 expression correlate with increased breast and lung cancer patients' survival, respectively." (PMID 26882547, 2016). "We demonstrate that miR‐515‐5p inhibits MARK4 directly 3′ UTR interaction and that MARK4 knock‐down mimics the effect of miR‐515‐5p on breast and lung cancer cell migration." (PMID 26882547, 2016). "Similarly, in the directional assay, the expression of MARK4 rescued the decrease in MDA‐MB‐231, A549 and H1299 cell migration, although this was more prominent for the lung cancer cell lines." (PMID 26882547, 2016).
type 2 diabetes (2 papers, 2017). "The MARK4 gene encodes a member of the microtubule affinity-regulating kinase family, and is inseparably linked with many human diseases, including cancer, diet-induced obesity, type 2 diabetes, and neurodegenerative disorders." (PMID 28122348, 2017).
atherosclerosis (1 paper, 2024). A disease characterized by the build-up of fatty material and calcium deposition in the arterial wall resulting in partial or complete occlusion of the arterial lumen. "Collectively, there is evidence pointing to a proatherogenic role for MARK4, rendering this kinase a potential therapeutic target in atherosclerosis." (PMID 38892400, 2024). "MARK1, MARK3, and MARK4 have been reported to activate Hippo kinases, which may have implications for atherosclerosis development since activation of the Hippo kinase (mammalian STE20-like) MST1 has been reported to suppress EC activation when exposed to disturbed flow." (PMID 38892400, 2024). "Therefore, MARK4 inhibitors, such as MARK4 inhibitors 1–4, may be worth exploring in an atherosclerosis model." (PMID 38892400, 2024). "Although the literature on the role of MARKs in atherosclerosis is rather limited, there are some reports on MARK2 and MARK4." (PMID 38892400, 2024).
autoimmune conditions (1 paper, 2017). "Novel gene-longevity associations included genes MICA/B (a locus previously linked to autoimmune conditions rheumatoid arthritis and multiple sclerosis), TOX, ZW10, SEMA6D, EGLN2/CYP2A6, EXOC3L2/MARK4 and C20orf187." (PMID 29227965, 2017).
depression (1 paper, 2023). "Given that the present study is a cross-sectional analysis of cortical physiology in LLD and there is no age-matched control group, we cannot assess whether the potential effects of MARK4 and PPP1R37 are related to depression, aging, or both." (PMID 37391420, 2023).
ischemic cardiomyopathy (1 paper, 2025). Ischemic cardiomyopathy is a cardiomyopathy in which a weakness in the muscle of the heart due to inadequate oxygen delivery to the myocardium with coronary artery disease being the most common cause. "In animal models of diabetic and ischemic cardiomyopathy, the expression of Mark4 mRNA, as well as the expression of MARK4 protein and the levels of detyrosinated microtubules were significantly elevated." (PMID 40332117, 2025). "In diabetic and ischemic cardiomyopathy, the expression of Mark4 mRNA as well as the expression of MARK4 protein were significantly elevated." (PMID 40332117, 2025).
metastatic disease (1 paper, 2016). "This link between changes in MARK4 expression and clinical metastatic disease was supported by our experimental data using animal models." (PMID 26882547, 2016). "In short, our data demonstrate that miR‐515‐5p dramatically inhibits cell migration by directly down‐regulating MARK4 expression in two different cancer types and suggests a role for miR‐515‐5p and MARK4 as potential biomarkers in metastatic disease and as possible therapeutic targets." (PMID 26882547, 2016). "However, while these data suggested that the miR‐515‐5p/MARK4 axis may be regulated in the context of metastatic disease, it did not draw a direct link between miR‐515‐5p expression levels and the onset of metastasis." (PMID 26882547, 2016).
neuro-degenerative diseases (1 paper, 2026). "We discuss how key regulators of this transition-including Cdk1, centrosomal γ-tubulin recruitment, Golgi-derived microtubule nucleation, and the kinase MARK4 may constitute druggable nodes to tune microglial reactivity in neuro-degenerative diseases." (PMID 42088827, 2026).
ovarian carcinoma (1 paper, 2017). A malignant neoplasm originating from the surface ovarian epithelium. "However, no research on MARK4 has been performed for ovarian cancer, so further study is required regarding its potential involvement in the metastasis of ovarian carcinomas." (PMID 28122348, 2017).
Parkinson disease (1 paper, 2023). A progressive degenerative disorder of the central nervous system characterized by loss of dopamine producing neurons in the substantia nigra and the presence of Lewy bodies in the substantia nigra and locus coeruleus. "MARK4 overexpression has been observed in the initiation of neurodegenerative diseases, such as AD and Parkinson's disease (PD)." (PMID 37287673, 2023).
periodontitis (1 paper, 2022). An acute or chronic inflammatory process that affects the tissues that surround and support the teeth. "Our present study further demonstrated that MARK4 has been implicated in bacteria-induced inflammasome activation in periodontitis." (PMID 34992737, 2022). "In conclusion, this study was the first to prove that MARK4 affects the NLRP3 inflammasome-dependent pyroptosis in periodontitis." (PMID 34992737, 2022). "MARK4 inhibition might be a potential target in regulating the NLRP3 inflammasome during periodontitis progress." (PMID 34992737, 2022). "This study aimed to explore whether microtubule affinity regulating kinase 4 (MARK4) can be a therapeutic target of periodontitis by affecting microtubule dynamics and NLRP3 inflammasome-mediated pyroptosis in macrophages." (PMID 34992737, 2022). "MARK4 may become a therapeutic target during the progress of periodontitis by regulating microtubule dynamics and NLRP3 inflammasome activation." (PMID 34992737, 2022).
polycystic ovary syndrome (1 paper, 2024). A disorder that manifests as multiple cysts on the ovaries. "Additionally, MARK4 expression is downregulated in women with ovulatory polycystic ovary syndrome, which inhibits follicular development and the ovulation process." (PMID 39273345, 2024).
prion disease (1 paper, 2023). A transmissible disease that is caused by a protein that is able to induce abnormal folding of normal cellular proteins, leading to characteristic spongiform brain changes, which are associated with neuronal loss without an inflammatory response. "Another kinase, microtubule affinity-regulating kinase 4 (MARK4), also turned out to be one of the proteins whose levels were decreased in prion diseases." (PMID 36352320, 2023).
Stroke (1 paper, 2019). Sudden impairment of blood flow to a part of the brain due to occlusion or rupture of an artery to the brain. "RNA-sequencing of stroke-injured layer 5 cortical neurons, identified the microtubule-associated regulatory kinase, Mark4, as significantly up-regulated after focal axonal ischemia." (PMID 31429800, 2019). "Stroke-induced up-regulation of Mark4 is associated with selective remodeling of the apical dendrite after stroke and the phosphorylation of tau in vivo." (PMID 31429800, 2019). "The ability of stroke-injured neurons to handle these potentially pathogenic modifications of tau induced by Mark4 over the long-term is unknown." (PMID 31429800, 2019). "To examine whether stroke-induced expression of Mark4 results in pathogenic tau phosphorylation, we examined murine tau phosphorylation after stroke using both immunofluorescence in stroke-injured neurons and electro-chemiluminescence immunoassay (ECLIA) for phospho-tau." (PMID 31429800, 2019). "Among the MARK enzyme isoforms, only Mark4 was enriched in stroke-injured cortical neurons." (PMID 31429800, 2019). "Protein transfection of ipsilateral overlying cortical homogenates at 7d after stroke into tau biosensor cells did not result in significant tau aggregation by FRET, nor did transfection of phosphorylated full-length recombinant human tau after pre-treatment with Mark4." (PMID 31429800, 2019).
triple-negative breast carcinoma (1 paper, 2022). An invasive breast carcinoma which is negative for expression of estrogen receptor (ER), progesterone receptor (PR), and human epidermal growth factor receptor 2 (HER2). "This event ultimately inhibits the Hippo kinase cascade to enhance triple-negative breast cancer (TNBC) metastasis by transcriptionally activating MARK4." (PMID 35449131, 2022).